IL6 (interleukin 6)
Diseases named in the same sentence as IL6 in open-access papers (continued):
Sharing a sentence is not in itself a finding about the gene and the disease.
breast cancer (continued). "There is limited evidence in the literature to date which explores IL6/JAK/STAT3 as prognostic or predictive biomarkers in breast cancer." (PMID 37199043, 2023). "Pre-treatment levels of IL-6, soluble TNFR I and II were significantly associated with four weeks post-treatment phenotypic frailty in the breast cancer group." (PMID 37213604, 2023). "BRD4 degrader reduced BRD4, PD-L1, RelB, and IL-6 levels and overexpression of PD-L1 of ARV-825 treated breast cancers increased reduced PD-L1, RelB, and IL-6 levels." (PMID 37924094, 2023). "We demonstrated that CAFs secreted high levels of IL-6 and IHC staining showed higher levels of IL-6 in stromal cells in breast cancer tissue compared with that in adjacent normal tissue." (PMID 36635302, 2023). "Elevated levels of IL-6 have also been demonstrated in women with breast cancer and can be one of the main reasons for anorexia/cachexia." (PMID 37298830, 2023). "In this study, we found that GREM2 suppressed adipocyte differentiation and that adipocytes overexpressing Grem2 reduced the production of several adipokines, including IL-6, contributing to the inhibition of breast cancer cell growth and lung metastasis." (PMID 37880751, 2023). "This is supported by the observation of an inverse correlation between IL10 and IL6 levels in breast cancer patients." (PMID 37238004, 2023). "In fact, autophagy in RAS-transformed mammary cancer cells induces tumor cell invasion and lung metastasis through multiple secretory factors including IL-6." (PMID 36831154, 2023). "As illustrated in, the A2AR is linked to the invasive breast cancer signature, oncogenic and angiogenic signaling pathways (Myc, VEGF and IL6-JAK-STAT3) as well as proliferation, metastasis, hypoxia, adhesion and cell cycle processes (Rac1 GTPASE cycle)." (PMID 37753093, 2023). "Among the fifteen best-ranked ferroptosis genes in breast cancer, eleven harbored some association with “extracellular matrix remodeling” literature in the PUBMED database, especially TNF, SET, and IL6, found to be highly cited in this specific literature." (PMID 37681908, 2023). "Local tumor overexpression of IL-6 has been observed in colorectal, prostate, pancreatic, lung, cervical, and breast cancer as well as in renal and ovarian carcinomas, confirming the important role of this cytokine in tumor survival and progression." (PMID 37763742, 2023). "Here, we demonstrated a crosstalk between IL-6 and progranulin signaling in breast cancer, involved in the induction of stem cell features through the receptor sortilin." (PMID 38136303, 2023). "In HCC and breast cancer, IL6 from TAMs activates the STAT3 pathway to promote CSC population, migration, and angiogenesis." (PMID 38035101, 2023). "The secretion of IL-6 by MSCs contributes to the development of chemotherapy resistance and encourages the proliferation of ERα+ breast cancer cells." (PMID 38001753, 2023). "Only changes in five analytes (CXCL5, CXCL1, CCL17, CXCL10, and IL-6) were seen to overlap across all four breast cancer cell-line EV-stimulated conditions." (PMID 37441083, 2023). "The JAK2-STAT3 and JAK2-STAT5 pathways have been demonstrated to be constitutively active in luminal breast cancer via the stimulation of IL-6 and PRL, respectively." (PMID 37834225, 2023). "After culturing adipocytes-mock or adipocytes-Grem2 on the transwells and MTV/TM-011 breast cancer cells on the bottom for 48 h, changes in IL-6 mRNA expression in breast cancer cells were examined." (PMID 37880751, 2023). "The overexpression of MCT-1 in triple-negative breast cancer activates MCT-1/miR-34a/IL-6/IL-6R signaling, disrupting the normal structure of breast cancer epithelial glands and inducing EMT, thus promoting the polarization of TAMs toward the M2 subtype." (PMID 38001753, 2023). "Treatment of breast cancer cell lines with recombinant IL6 reproduced this effect, identifying IL6 as the first ER-independent regulatory system governing RET expression in breast cancer." (PMID 36918928, 2023).
breast cancer (continued). "On the other hand, some investigations have demonstrated an increase in IL-6 following breast cancer treatment, plausibly due to a normal inflammatory response as a result of introducing chemo-toxicants into the body." (PMID 37181043, 2023). "The GPX8/IL-6/STAT3 axis has been shown to maintain an aggressive breast cancer phenotype, and GPX8 itself mediates the proliferation and migration of GBM cells." (PMID 37795080, 2023). "The most frequently mentioned biomarkers for this cancer type came from the interleukin superfamily including IL-6, IL-8, IL-10, IL-2, IL-18, which is quite similar to what was found in breast cancer." (PMID 37181043, 2023). "A systematic review by Tyagi et al14 presented that IL‐6, IL‐1β, and TNF‐α were associated with cognitive dysfunction in post‐chemotherapy breast cancer patients." (PMID 36965094, 2023). "Overall, our results demonstrate that PPMPs can promote tumor progression by promoting the inflammatory cytokine IL-6 secretion and cell cycle progression in breast cancer cells." (PMID 37069244, 2023). "By further examining the relationship between IL-6 and progranulin protein expression in breast cancer, we identified a crosstalk between progranulin and IL-6 protein expression, where IL-6 also induced progranulin protein expression." (PMID 38136303, 2023). "Breast cancer-secreted IL-6 was found to orchestrate a chain of events, beginning with the upregulation of KDM2A in mammary fibroblasts through the STAT3/NFκB p50 axis." (PMID 37821959, 2023). "The aim of this study was to establish a prognostic role for IL6/JAK/STAT3 signalling pathway members in a larger retrospective cohort of breast cancer patients (n = 850) with a focus on TNBC." (PMID 37199043, 2023). "It is known that IL-6 can promote breast cancer progression through increasing cell invasion, angiogenesis, and metastasis." (PMID 36979654, 2023). "It is undeniable that IL-6 is usually secreted at high levels in the breast cancer microenvironment." (PMID 37978384, 2023). "Missing moderator variables for breast cancer were 0.3% for chemotherapy, 25.2% for IL6, and 24.8% for TNFα." (PMID 36658635, 2023). "We observed upregulation of the IL-6 cytokine in the supernatant of EV-stimulated PBMCs across all four breast cancer subtypes." (PMID 37441083, 2023). "The activation of STING-regulated IL-6/STAT3 increases the expression of PD-1 ligand in breast cancer." (PMID 37051596, 2023). "In conclusion, this supplementation improved the PUFA status and decreased the level of IL-6 in breast cancer patients undergoing chemotherapy." (PMID 37081029, 2023). "For example, excreted from breast cancer, miR-183-5p enhanced NF-κB signaling and promoted IL-1β, IL-6, and TNF-α expression in TAM." (PMID 37273004, 2023). "Likewise, pre-clinical investigations revealed that targeting of the IL6 signaling might be beneficial for other cancers as well, where bad prognosis is associated with high IL6 level such as renal cell carcinoma, non-small cell lung cancer, and breast cancer." (PMID 37006265, 2023). "In breast cancer, IL-6 is found to be overexpressed and has been described as a tumor-promoting cytokine through its major effector STAT3." (PMID 36835413, 2023). "In conclusion, the interplay between progranulin and IL-6 highlights a dual breast cancer stem cell-promoting function via sortilin, further supporting sortilin as a highly relevant therapeutic target for aggressive breast cancer." (PMID 38136303, 2023). "Research has reported that the level of IL-6 is high in the serum of patients with breast cancer and LC, and the high IL-6 level is correlated with poor clinical prognosis." (PMID 37901456, 2023). "These co-culture systems allowed us to unmask how TGF-β, PDGF and IL-6 mediate the interplay between mammary tumor cells and fibroblasts." (PMID 37173963, 2023). "Taking advantage of these tools, we unmasked how TGF-β, PDGF and IL-6 mediate the interplay between mammary tumor cells and fibroblasts." (PMID 37173963, 2023).
breast cancer (continued). "Even though IL-6 is considered a pro-inflammatory cytokine, it has been investigated as a target in breast cancer, namely for the estrogen receptor modulator bazedoxifene." (PMID 37174080, 2023). "This study has revealed a profound association between high protein expression of IL6/JAK/STAT3 signalling and worse clinical outcomes in a large retrospective cohort of breast cancer patients." (PMID 37199043, 2023). "To examine effects of Grem2-overexpressing adipocytes and IL-6 protein on invasive capacity of breast cancer cells, we performed a 3D invasion assay." (PMID 37880751, 2023). "The screening results showed that none of the receptors for Cx3cl1 (CX3CR1), Cxcl16 (CXCR6), Ccl17 (CCR4, DARC, CCR10) or IL6 (IL6R) was more expressed in basal B compared to basal A or luminal breast cancer cells." (PMID 38055067, 2023). "Activation of the IL6/STAT3/ NF-κB signaling pathway in HER2-positive PTEN-depleted breast cancer cells induces an increase in the CSC population." (PMID 36632469, 2023). "Activation of IL-6 inflammatory loop-induced trastuzumab resistance in breast cancer mouse xenografts." (PMID 37480115, 2023). "Taken together, these results indicate that overexpressing Grem2 in adipocytes can reduce breast cancer cell proliferation and lung metastasis in vivo and IL-6 can reverse these effects." (PMID 37880751, 2023). "In light of the many similarities between ovarian and breast cancer, such as hormone response and estrogen receptor distribution, IL-6 appears to play the same role in regulating EMT in EOC as that in breast cancer." (PMID 36814597, 2023). "In a previous study, pro-inflammatory cytokine IL-6 was higher in a highly invasive breast cancer cell line MDA-MB-231 than a low invasive cancer cell line MCF-7." (PMID 37501379, 2023). "IL-6-induced EMT and chemoresistance have also been demonstrated in luminal breast cancers via a mechanism that involves the IL-6/JAK/STAT3 signaling axis, one of the most promising therapeutic targets for cancer control under clinical investigation." (PMID 37173963, 2023). "The results showed that CAF-derived IL-6 induces the growth and radioresistance of breast cancer cells both in vitro and in vivo." (PMID 36635302, 2023). "In breast cancer, higher expression of IL-6 and DCLK1 predicts shorter recurrence-free survival in TNBC but not in luminal A, luminal B and HER2 subtypes, which suggests the critical roles of DCLK1 and IL-6 in tumor recurrence of TNBC." (PMID 37069669, 2023). "IL6/JAK/STAT3 signalling is upregulated in breast cancer; however, there is limited evidence for its role in TNBC." (PMID 37199043, 2023). "Another approach in targeting secretome is using drugs that block specific molecules’ secretion rate, such as IL-6, to reduce breast cancer proliferation." (PMID 37174117, 2023). "The qRT-PCR and IF assays also indicated similar expression changes of Survivin and IL6 in breast cancer cells." (PMID 37454220, 2023). "Adipocyte-derived IL-6 and leptin can promote breast cancer metastasis by promoting the expression of lysyl hydroxylase." (PMID 37880751, 2023). "Induced by the cytokine IL-6, functional roles for Stat3 in inducing breast cancer growth and driving breast cancer metastasis have recently been reported." (PMID 36266450, 2023). "CXCL1 can also indirectly induce the EMT of breast cancer cells through recruiting MDSC, which then causes the EMT of breast cancer cells via IL-6." (PMID 37108425, 2023). "Our recent study found that the pro-inflammatory cytokine IL-6, released by breast cancer cells, can increase the expression of KDM2A, thereby promoting the transformation of CAFs." (PMID 37821959, 2023). "In terms of fibronectin production, the breast cancer cells used in our study were more responsive to IL-1β than to TNF-α or IL-6." (PMID 36922898, 2023). "IL-6 levels involved in clinical tumor stages and pathological grades in breast cancer; high IL-6 levels indicate poor prognosis in breast cancer patients." (PMID 36693957, 2023).
breast cancer (continued). "IL6/IL8 ratio larger than 2.0 induced cellular proliferation of MCF-7 (breast cancer transformed cell line) - more cancer cell proliferation, worse disease prognosis." (PMID 37181043, 2023). "In this study, we observed that PPMPs with irregular shapes affected human breast cancer cells; notably, exposure to PPMPs increased cell cycle-related gene expression and IL-6 secretion from MDA-MB-231 and MCF7 cells." (PMID 37069244, 2023). "In particular, in the co-culture of endotoxin-tolerant macrophages and breast cancer cells, the IL-6 expression appeared to be at a level comparable to that of the monoculture of endotoxin-tolerant macrophages." (PMID 37894480, 2023). "Consistently, IHC staining showed that compared with that in adjacent normal tissue, the stromal cells in breast cancer tissues expressed high levels of IL-6." (PMID 36635302, 2023). "Three key inflammatory biomarkers associated with inflammation in breast cancer survivors are CRP, IL-6, and IL-18." (PMID 36717689, 2023). "Evaluation of the cytokine profiles of Black and white women with breast cancer uncovered a higher expression of Resistin and IL6 in the serum samples of Black women." (PMID 36702853, 2023). "In breast cancer, Jagged1 expression can also drive this cycle through activation of the Notch signaling pathway and the release of IL-6 and TGF-β." (PMID 37440925, 2023). "Treatment-naïve breast cancer patients and age-matched healthy donors were assessed for responsiveness of peripheral T, B, NK, and myeloid cells to IL-6 using phosphoflow cytometry." (PMID 37741983, 2023). "Serum IL-6 levels are positively correlated with serum VEGF levels in breast cancer patients, which can promote angiogenesis and metastasis." (PMID 37880751, 2023). "A growing body of reports demonstrates a strong correlation between IL6 levels and the invasiveness of breast cancer." (PMID 36982207, 2023). "In fact, it has been reported that IL-6 inhibits anticancer immune responses generated by cytotoxic chemotherapy, and promotes breast cancer metastasis suppressing the anti-tumor immune response via IL-6/JAK/STAT3 signaling." (PMID 38239364, 2023). "In conclusion, combining cryo-thermal therapy with anti-IL-6 treatment induced CD4+ Th1-dominant immunity to achieve long-term survival of breast cancer-bearing mice with an MDSC-dominated immunosuppressive environment." (PMID 37108179, 2023). "In breast cancer, other cytokines such as IL‐6, IL‐1α, IL‐1β, IL‐8, TNF‐α/β, TGF‐β, and GM‐CSF are also known to stimulate angiogenesis." (PMID 36815234, 2023). "Clinical data from several studies show that taxane therapy increases serum IL-6 and G-CSF levels in patients and that higher levels of serum IL-6 is a prognostic marker for early breast cancer recurrence in patients receiving systemic therapy." (PMID 37699010, 2023). "Clinically, serum IL-6 concentrations were significantly higher in patients with breast cancer compared with healthy controls, and IL-6 serum levels were significantly higher in patients with metastatic breast cancer than patients without metastasis." (PMID 36765683, 2023). "Pracinostat (SB939) attenuated tumor growth and metastasis via blocking the IL6/STAT3 pathway in breast cancer." (PMID 36969235, 2023). "Studies have indicated that Faecalibacterium can produce SCFAs, particularly butyric acid in the intestine, inhibit the secretion of IL-6 and IL-8 in cells, and help prevent breast cancer." (PMID 37106863, 2023). "In breast cancer, the IL-6 signaling axis is a promising therapeutic target since it promotes growth and invasion, mediates the spread of metastatic capabilities, and is associated with poor prognosis." (PMID 37174117, 2023). "The most frequently measured biomarkers in breast cancer came from the interleukin family, with IL-6 being the most prevalent." (PMID 37181043, 2023).
breast cancer (continued). "Regular exercise in breast cancer survivors after primary treatment has consistently shown to decrease pro-inflammatory cytokines (IL-2, IL-6, IL-8, TNF-α) and increase anti-inflammatory cytokines (IL-10)." (PMID 37507961, 2023). "EMT significantly alters the dynamic environment of TME, drawing stromal and immune cells from different tissues to the TME through cytokines (such as TGF-β) and chemokines (such as CXCL2, CCL22, MMP, IL-6, and IL-8) released by breast cancer cells." (PMID 37174117, 2023). "Higher serum IL-6 levels in breast cancer patients correlate with clinical stage, poor prognosis, and a low survival rate." (PMID 36794014, 2023). "In ovarian and breast cancers, IL-6-induced systemic inflammation enhances the mobilization of myeloid-derived suppressor cells which primed ɣδ T cells to produce galectin-1, thereby abolishing anti-tumor immunity." (PMID 36873388, 2023). "Our analysis revealed that 4T1 breast cancer triggered various inflammatory responses in the livers as exemplified by the activation of the interleukin-6 (IL-6) signaling." (PMID 36817472, 2023). "Taken together, this evidence suggests that the IL-6/JAK-STAT3 loop plays a basic role in luminal breast cancer progression and deserves further research." (PMID 37834225, 2023). "IL-6 is a known mediator of the EMT process in breast carcinomas, and it was shown that SDC1 silencing suppresses IL-6 signaling pathways, resulting in less proliferative and metastatic behavior." (PMID 36980680, 2023). "In this context, Ravishankaran and Karunanithi (2011) observed a correlation between IL-6 concentrations and tumor staging in women with breast carcinoma, with higher levels in patients with detectable metastases." (PMID 36899784, 2023). "Further, it has been explored that C15:0 has an inhibitory effect on the IL-6-induced JAK2/STAT3 signaling pathway in human breast carcinoma cells, considering C15:0 as a promising therapeutic strategy to treat human cancers." (PMID 37432205, 2023). "In the 4T1-related breast carcinoma model, mixed leucocyte cultures of tumor-bearing mice secrete markedly higher levels of IL-6 and TNF-α, and lower levels of IFN-γ." (PMID 37371563, 2023). "A distinctive feature is a higher correlation of its content with HER2-positive status and a low level of Ki-67 expression, which, accordingly, determines a higher level of IL-6 in saliva in luminal B (HER2-positive) breast cancer." (PMID 36286034, 2022). "This indicates that breast cancer cells upregulate OPG in breast stromal fibroblasts through the IL-6 protein and its canonical STAT3 pathway." (PMID 36359766, 2022). "The data reviewed here clearly show that IL-6 cytokine family plays an important role in breast cancer progression." (PMID 35163731, 2022). "Another study on breast cancer found that PNU-74654 modulated the pro-inflammatory cytokine IL-6, which is related to leukocyte recruitment." (PMID 35744061, 2022). "In a mouse breast cancer model, a population of cancer cells producing the pro-inflammatory cytokines IL-6 and IL-8 correlated with the promotion of tumor cell migration." (PMID 35769460, 2022). "Specifically, we found that elevated plasma IL-6 and TNF-α levels were associated with higher DepS risk, which was consistent with the previous research in breast cancer patients receiving adjuvant therapy." (PMID 36615742, 2022). "In addition, we showed that core fucosylation of integrin αvβ5 or IL6ST might be crucial for breast cancer cell adhesion to vitronectin or enhanced cellular signaling to interleukin 6 and oncostatin M, two cytokines implicated in the breast cancer epithelial–mesenchymal transition and metastasis." (PMID 35303925, 2022). "For example, the oncogene Multiple Copies in T-cell Malignancy-1 (MCT-1), a recently identified prognostic biomarker in aggressive breast cancers, stimulates M2 macrophages in the tumor microenvironment through stimulation of IL-6." (PMID 35371975, 2022).